KL (klotho)
Diseases named in the same sentence as KL in open-access papers (continued):
Sharing a sentence is not in itself a finding about the gene and the disease.
pancreatic adenocarcinoma (2 papers, 2020 to 2023). "Taken together, these data provide evidence to support the further development of Klotho as a prognostic marker in pancreatic adenocarcinoma." (PMID 37958253, 2023). "Pancreatic adenocarcinoma tissue or human pancreatic adenocarcinoma cell lines Panc1, MiaPaCa2, and Colo357 are characterized by reduced KL expression compared to normal pancreatic tissue." (PMID 33520985, 2020). "miR-199a lowers KL expression in pancreatic adenocarcinoma Panc1 cells." (PMID 33520985, 2020). "A single study addressed the role of αKlotho in pancreatic adenocarcinoma and concluded that KLA gene expression levels and promoter methylation may have prognostic value, as increased KLA promoter methylation and decreased mRNA expression levels were associated with lower patient survival." (PMID 37958253, 2023).
polycystic ovary syndrome (2 papers, 2022). A disorder that manifests as multiple cysts on the ovaries. "Likewise, serum klotho levels were negatively correlated with waist circumference and BMI among women aged 19–33 years with polycystic ovary syndrome." (PMID 36061981, 2022). "Two AREs have been identified in silico in the human klotho promoter region which may explain the higher klotho protein levels in the granulosa cells from women with Polycystic ovary syndrome (PCOS) and hyperandrogenism compared to controls." (PMID 35434614, 2022).
rectal cancer (2 papers, 2021 to 2023). A primary or metastatic malignant neoplasm that affects the rectum. "This study also evaluated the correlation of BRCA1, CLU, AGTR1, and KL expression with methylation levels in rectal cancer." (PMID 35083278, 2021). "Through the cBioPortal tool, we evaluated CNAs of BRCA1, CLU, AGTR1, and KL across rectal cancer." (PMID 35083278, 2021).
rhabdomyolysis (2 papers, 2021 to 2022). Necrosis or disintegration of skeletal muscle often followed by myoglobinuria. "Klotho silencing leads to an aggravated inflammatory response in a rhabdomyolysis model, causing higher expression of TNF-α and IL-1β, when compared to control mice injected with siRNA-control." (PMID 35056905, 2021). "Likewise, in an AKI mouse model of rhabdomyolysis, the modified MSCs with the Klotho gene presented markedly higher therapeutic potential when compared to the transplantation of MSC-EVs and MSCs alone." (PMID 35056905, 2021). "Based on the present findings, guanosine may be considered as a promising agent in the protection against or treatment of rhabdomyolysis-induced AKI because of its capability of inducing Klotho gene expression that may help in reducing apoptosis and oxidative stress and increasing renal TAC." (PMID 35656176, 2022). "The protective effect of guanosine has been already evaluated in renal damage induced by ischemia-reperfusion; however, its role in rhabdomyolysis-induced AKI and its relation to Klotho gene modification has not been evaluated yet, to the researcher’s best knowledge." (PMID 35656176, 2022).
Shock (2 papers, 2020 to 2022). The state in which profound and widespread reduction of effective tissue perfusion leads first to reversible, and then if prolonged, to irreversible cellular injury. "Paradoxically, it has been previously demonstrated that S-Klotho plasma levels are increased in critical illness patients (i.e., septic shock) where there is a clear pro-inflammatory state." (PMID 31973171, 2020).
sickle cell disease (2 papers, 2022 to 2024). Sickle cell anemias are chronic hemolytic diseases that may induce three types of acute accidents: severe anemia, severe bacterial infections, and ischemic vasoocclusive accidents (VOA) caused by sickle-shaped red blood cells obstructing small blood vessels and capillaries. "Furthermore, the Cooperative Study of Sickle Cell Disease (CSSCD) DNA samples have identified certain candidate gene SNPs (e.g., BMP6, annexin A2, and klotho) as risk factors for the development of avascular necrosis of the hip and/or shoulder." (PMID 39113817, 2024). "The results indicate that polymorphisms in the genes of the bone morphogenetic protein 6 (BMP6), Klotho (KL) and Annexin A2 (ANXA2) may be associated with osteonecrosis in the context of sickle cell disease." (PMID 35584416, 2022). "The results indicate that the polymorphisms in BMP6, Klotho and ANXA2 genes may be associated with avascular necrosis in patients with sickle cell disease." (PMID 35584416, 2022).
skin cancer (2 papers, 2023). "In unadjusted linear regression models, each ng/mL increase in Klotho was associated with a 40% lower odds of skin cancer history (odds ratio [OR], 0.60; 95% CI, 0.40-0.90; P =.02)." (PMID 37752937, 2023). "However, no large epidemiologic studies have investigated a relationship between Klotho levels and skin cancer risk." (PMID 37752937, 2023). "Further research is needed to clarify the relationship between Klotho and skin cancer." (PMID 37752937, 2023). "We found a significant inverse relationship between Klotho levels and a history of skin cancer." (PMID 37752937, 2023). "In addition, since no research on skin cancer and Klotho has been found yet, we suspect that this may be the first to find an association between serum Klotho and skin cancer." (PMID 35841322, 2023). "Subjects with a history of skin cancer had significantly lower Klotho levels than those without (0.80 vs 0.86 ng/mL; P <.001)." (PMID 37752937, 2023).
small cell lung carcinoma (2 papers, 2015 to 2020). Small cell lung cancer (SCLC) is a highly aggressive malignant neoplasm, accounting for 10-15% of lung cancer cases, characterized byrapid growth, and early metastasis. "Patients with large-cell neuroendocrine lung carcinoma or small-cell lung cancer with KL expression have better outcome than those without KL expression pointing to KL being a potential biomarker." (PMID 33520985, 2020). "We found klotho IHC staining in all MM samples tested, while a small sample of normal plasma cells and MGUS bone marrow aspirates was negative with a well-characterized monoclonal antibody previously used in kidney and in small cell lung cancer samples." (PMID 25944690, 2015).
T-cell lymphoma (2 papers, 2020 to 2024). "Patients with T-cell lymphoma have much lower levels of Klotho in their lymph nodes than in normal lymph nodes; the overexpression of Klotho can control the growth of T-cell lymphomas and decrease insulin-like growth factor-1 receptor (IGF-1R) signaling, which has anticancer properties." (PMID 39308872, 2024). "Moreover, in biopsies and cell lines of T-cell lymphoma and DLBLC, KL expression is reduced correlating with shorter survival." (PMID 33520985, 2020).
thymic atrophy (2 papers, 2019). "Together, this detailed analysis of the thymus shows that hypomorphic expression of Klotho did not impair T cell development and that age-related thymic atrophy occurred normally in B6-kl/kl mice compared to C57BL/6 mice." (PMID 31386628, 2019).
thyroid disorders (2 papers, 2015 to 2024). "First, as this paper is a cross-sectional study, causality cannot be inferred and future longitudinal studies are needed to determine the predictive value of Klotho in thyroid disorders." (PMID 38696398, 2024). "The positive associations between fT3 and dp-ucMGP and sKlotho suggest that synthesis of MGP and Klotho is influenced by thyroid hormones, and supports a link between non-thyroidal illness and alterations in calcification inhibitor levels." (PMID 26147960, 2015).
urolithiasis (2 papers, 2022). Stone(s) within the urinary tract. "Several KL (α-klotho) gene polymorphisms have previously been reported in association with urolithiasis, cardiovascular disease, cancers and longevity." (PMID 34542150, 2022).
valvular heart disease (2 papers, 2014 to 2020). "We speculate that insufficiency of this anti-aging protein may have a role in the pathogenesis of CAVD, an aging-related valvular heart disease, and that recombinant Klotho may have therapeutic potential to prevent CAVD progression." (PMID 32046115, 2020).
Ventricular arrhythmia (2 papers, 2022 to 2025). "In this context, enhancing Klotho availability appears to be a valid therapeutic strategy to prevent acquired long QT syndrome and potentially fatal ventricular arrhythmias and SCD in CKD." (PMID 35042527, 2022). "Our study underscores the potential of exogenous Klotho supplementation as a novel protective measure against ischaemic HF, reducing the development of detrimental cardiac remodelling and of critical post‐MI complications, such as ventricular arrhythmia." (PMID 39815421, 2025).
abdominal aortic aneurysm (1 paper, 2025). Enlargement and ballooning of the vessel that supplies arterial blood to the abdomen, pelvis and legs. "Considering that abdominal aortic aneurysm, an extracranial subtype of IA, has some similarities with the pathogenesis of IA, we hypothesized that KL deficiency may influence IA, which is consistent with our findings." (PMID 38977622, 2025).
Acidosis (1 paper, 2024). Abnormal acid accumulation or depletion of base. "The favorable effect of exercise on serum concentrations of Klotho and FGF-23 may be related to better control of oxidative stress, chronic inflammation and metabolic acidosis that develops as a result of energy wasting." (PMID 38169578, 2024).
acquired long QT syndrome (1 paper, 2022). A form of long QT syndrome in which malfunction of the cardiac ion channels is caused by drugs or metabolic abnormalities. "The present work demonstrates that improving Klotho availability prevents the acquired long QT syndrome associated with CKD." (PMID 35042527, 2022).
acute coronary syndrome (1 paper, 2024). Signs and symptoms related to acute ischemia of the myocardium secondary to coronary artery disease. "Therefore, we conducted a study to investigate the potential correlation between serum Klotho and outcomes in patients with acute coronary syndrome (ACS)." (PMID 39330350, 2024). "The evolution of Klotho in the development of acute coronary syndrome (ACS) has not been previously reported." (PMID 39330350, 2024). "Nevertheless, the levels of serum Klotho in acute coronary syndrome (ACS) have not been reported." (PMID 39330350, 2024).
acute pancreatitis (1 paper, 2021). An acute inflammatory process that leads to necrosis of the pancreatic parenchyma. "Furthermore, as demonstrated in vitro, by transferring exosomes from cells with Klotho overexpression to pancreatic cell cultures, in which acute pancreatitis has been induced, Klotho inhibited NF-κB activation and inflammation in these cells and inhibited apoptotic pancreatic cell loss." (PMID 33478014, 2021).
acute tubular necrosis (1 paper, 2023). "Renal biopsy specimens from AKI patients diagnosed with acute tubular necrosis or acute tubulointerstitial nephritis showed lower Klotho protein abundance to be correlated with AKI severity." (PMID 37892163, 2023).
age-related macular degeneration (1 paper, 2024). Age-related loss of vision in the central portion of the retina (macula), secondary to retinal degeneration. "Klotho may also play a role in age-related macular degeneration (AMD)." (PMID 39272986, 2024).
AIDS (1 paper, 2025). A syndrome resulting from the acquired deficiency of cellular immunity caused by the human immunodeficiency virus (HIV). "We employed a two-sample Mendelian randomization (MR) analysis to scrutinize the causal links between Klotho and 15 AIDs." (PMID 40797493, 2025). "In this investigation, we employed a two-sample MR approach to explore the causal association between Klotho and 15 AIDs." (PMID 40797493, 2025).
alcoholic liver diseases (1 paper, 2022). A disorder caused by damage to the liver parenchyma due to alcohol consumption. "All these data suggest that Klotho levels increase in patients with alcoholic liver disease, keeping a relationship with liver function impairment." (PMID 36009045, 2022). "The aim of this study was to analyze the relationship between Klotho and the serum levels of the inflammatory markers in alcoholic liver disease and to assess its prognostic value." (PMID 36009045, 2022). "In summary, Klotho, MDA, IL-8, and IL-6 behave similarly in patients with alcoholic liver disease, being more or less intensely related to disease progression and liver function impairment." (PMID 36009045, 2022).
allergic asthma (1 paper, 2020). A asthma with a basis in a pathological type I hypersensitivity reaction. "Our results indicate that eosinophils are decreased in the lungs of klotho WT mice after infection with A. baumannii, implying the inhibition of airway eosinophilia in young hosts with allergic asthma." (PMID 33329595, 2020). "However, the significant increase in eosinophils in the lungs of klotho KO mice after infection with A. baumannii indicates further induction of airway eosinophilia in elderly people with allergic asthma." (PMID 33329595, 2020).
Allergy (1 paper, 2024). An allergy is an immune response or reaction to substances that are usually not harmful. "Formal statistical analyses show that IL-6 rs1800795GG, IL-10RB rs2834167G positive genotypes, IL-13 rs1800925CC, CD23 rs2228137TT Klotho rs564481TT, might be risk factors for allergy." (PMID 39202464, 2024). "Finally, the Klotho rs564481 TT genotype was increased in allergy." (PMID 39202464, 2024).
ankylosing spondylitis (1 paper, 2025). An autoimmune chronic inflammatory disorder characterized by inflammation in the vertebral joints of the spine and sacroiliac joints. "This study differs from previous work by examining blood Klotho levels together with the Atherosclerosis Index (AI) and SCORE-based cardiovascular risk in patients with Ankylosing Spondylitis (AS)." (PMID 41517379, 2025).
aortic valve disease (1 paper, 2022). "Among these, a mouse model of premature aging (Klotho−/−) and heterozygote Npr2+/− and tissue-specific Sox9 mutants represents models in which genetic modification alone results in aortic valve disease." (PMID 36005436, 2022).
aortic valve stenosis (1 paper, 2016). Aortic valve stenosis (AVS) is a condition characterized by narrowing of the heart's aortic valve opening. "Aortic valve stenosis, which is the most common valvular disease in the elderly population, is associated with a decline in serum levels of Klotho." (PMID 27242197, 2016).
atrial tachycardia (1 paper, 2022). A disorder characterized by an electrocardiographic finding of an organized, regular atrial rhythm with atrial rate between 101 and 240 beats per minute. "Klotho can upregulate the expression of heat shock proteins, which protect from atrial tachycardia-induced remodeling and AF perpetuation." (PMID 35884879, 2022).
autism (1 paper, 2024). Persistent deficits in social interaction and communication and interaction as well as a markedly restricted repertoire of activity and interest as well as repetitive patterns of behavior. "In contrast, miR-150-5p, which targets the autism-associated Foxp169 transcript, declined with age in live human neurons, Klotho KO and by both age and APP pathology in AD mice models." (PMID 38862813, 2024).
autoimmune thyroiditis (1 paper, 2024). "In Model 2, compared to the first quartile, ln Klotho in the Q2 group was independently associated with autoimmune thyroiditis (OR = 1.49; 95% CI 1.05–2.12)." (PMID 38769411, 2024). "Additionally, we utilized a multivariable logistic regression model to investigate the association between serum Klotho levels and the degree of hypothyroidism (clinical/subclinical), as well as autoimmune thyroiditis." (PMID 38769411, 2024).
autosomal recessive hypophosphatemic rickets (1 paper, 2019). Autosomal recessive hypophosphatemic rickets (ARHR) is a hereditary renal phosphate-wasting disorder characterized by hypophosphatemia, rickets and/or osteomalacia and slow growth. "The three forms of autosomal recessive hypophosphatemic rickets (ARHR) result from mutations in DMP1 [ARHR1,], ENPP1 [ARHR2,], and FAM20C [ARHR3,], while hypophosphatemic rickets and hyperparathyroidism (HRHPT) is caused by mutations that upregulate KLOTHO expression." (PMID 30808384, 2019).
B-cell lymphomas (1 paper, 2025). "This study aimed to investigate a causal association between Klotho levels and the risk of B-cell lymphoma using a Mendelian randomization (MR) approach." (PMID 41261673, 2025). "First, in vitro studies using B-cell lymphoma cell lines are needed to investigate potential context-dependent biological roles of Klotho, particularly its impact on key signaling pathways like PI3K/AKT and NF-kB." (PMID 41261673, 2025). "Despite earlier studies suggesting potential suppressive effects of Klotho on lymphoma progression, B-cell lymphoma cohort analysis using GWAS data from the FINN Large Cohort did not support a significant role for Klotho in influencing B-cell lymphoma risk." (PMID 41261673, 2025). "Our comprehensive MR analysis suggests no causal relationship exists between Klotho levels and the risk of developing B-cell lymphomas." (PMID 41261673, 2025). "However, the role of Klotho in hematological malignancies like B-cell lymphoma appears less definitive." (PMID 41261673, 2025). "For instance, while enhancing Klotho expression might benefit therapies in certain solid tumors, its relevance in the treatment or prevention of B-cell lymphoma remains uncertain." (PMID 41261673, 2025). "Alternatively, the presence of other overriding or confounding biological factors might obscure Klotho effects in B-cell lymphoma." (PMID 41261673, 2025). "Our results did not reveal a causal relationship between Klotho protein levels and the risk of B-cell lymphoma." (PMID 41261673, 2025). "Third, the present study assumes a linear relationship between circulating Klotho levels and B-cell lymphoma risk; if the true association is nonlinear or threshold-dependent, our methods may not capture it." (PMID 41261673, 2025).
behavioral disorders (1 paper, 2023). "It has been shown that Klotho deficiency can also promote several neuropathologies related to the central nervous system, including loss of synapses and modulation of their plasticity, behavioral disorders, neuritis, and neurodegeneration." (PMID 37894946, 2023). "It has been proven that a Klotho deficit may contribute to the development of various nervous system pathologies, such as behavioral disorders or neurodegeneration." (PMID 37894946, 2023).
brain tumors (1 paper, 2025). "We found only a limited number of studies analyzing the role of Klotho in brain tumors." (PMID 39796185, 2025).
Bullous Keratopathy (1 paper, 2024). "Furthermore, guttae formation and the desquamation of wing cells were significantly increased with the Klotho loss of function, comparable to the conditions of Fuchs endothelial corneal dystrophy and bullous keratopathy." (PMID 38534403, 2024). "These pathological features support the use of Klotho mutant mice for investigating age-related cornea anomalies, including Fuchs endothelial corneal dystrophy, bullous keratopathy, and dry eye diseases." (PMID 38534403, 2024). "Furthermore, guttae formation and the desquamation of wing cells were significantly increased in the Klotho loss-of-function mutant mice, comparable to the conditions of FECD and bullous keratopathy." (PMID 38534403, 2024).
Calcium nephrolithiasis (1 paper, 2021). The presence of calcium-containing calculi (stones) in the kidneys. "There is also a contributing role of FGF-23 and Klotho gene polymorphism in the pathogenesis of calcium nephrolithiasis." (PMID 34249532, 2021).
carotid atherosclerosis (1 paper, 2025). A thickening and loss of elasticity of the walls of carotid arteries that occur with formation of atherosclerotic plaques. "Moreover, in individuals with carotid atherosclerosis, lower klotho protein levels in the blood and reduced KL gene expression in vascular tissues were observed alongside higher carotid-intima media thickness values." (PMID 40076542, 2025).